HMGB1 (high mobility group box 1)
Diseases named in the same sentence as HMGB1 in open-access papers (continued):
Sharing a sentence is not in itself a finding about the gene and the disease.
tumor (continued). "The dying tumor cells release tumor antigens and adjuvant molecules (ATP, HMGB1, and ecto-calreticulin) that trigger the involvement of macrophages in the immune response." (PMID 36679900, 2022). "Nevertheless, the photographic images of resected tumor and immunohistochemical staining support the findings that the HMGB1/B-cell axis alters CD31 in established lesions." (PMID 34617194, 2022). "Tumor cells have high concentrations of CXCL12 suspected to be due to the overexpression of high mobility group box 1 (HMGB1), an overexpressed protein by metabolically stressed cancer cells that captures CXCL12." (PMID 35844304, 2022). "HMGB1 is present in high concentrations in the TME mainly due to its production or release by both tumor cells and infiltrating inflammatory cells, and thus favors the establishment of a highly immunosuppressive TME." (PMID 35727208, 2022). "Of course, further related evidence needs to be obtained to further confirm that the high expression of HMGB1 plays a vital role in some tumors or the results in resistance to tumor changes in normal tissue." (PMID 36230798, 2022). "HMGB1 is highly expressed in a range of tumor tissues, and its subcellular localization determines the manner in which HMGB1 exerts its regulatory function on cancer." (PMID 35637945, 2022). "In this study, we constructed an oHSV expressing HMGB1 which was reported as a potential anticancer protein capable of killing tumor cells during hypoxia or normoxia." (PMID 35477503, 2022). "Tumor cells were also induced to release a large amount of HMGB1 in conditioned media after oAd-mCD47nb-Fc or oAd-ctr infection." (PMID 35837100, 2022). "High-mobility group box 1 (HMGB1), released by dying tumor cells, on the other hand, interacts with TLR4 on platelets and mediates platelet–tumor cell interaction, promoting metastasis." (PMID 35409226, 2022). "In contrast to M1 macrophages, HMGB1-dependent stimulation of RAGE facilitated pro-tumor activity in M2 macrophages." (PMID 36686729, 2022). "One critical question was then raised: What are the functions of these high levels of HMGB1 in tumor nest?" (PMID 34617194, 2022). "On the other hand, HMGB1 plays a protective role in the suppression of tumour and tumour chemoradiotherapy and immunotherapy." (PMID 35344301, 2022). "A correlation was also noted between the plasma HMGB1 concentrations and HMGB1 expression levels in tumor tissue." (PMID 35328684, 2022). "Early studies showed that HMGB1 levels are highly correlated with the depth of invasion, lymph node metastasis, tumor size and poor prognosis of GC." (PMID 36275647, 2022). "A previous report demonstrated that tumor irradiation at an extremely high dose (e.g., 20 Gy) induced the higher amount of HMGB-1 release; up to 16 Gy or its biologically equivalent dose, 8 Gy × 3 fr, was used to avoid normal tissue toxicity in vivo." (PMID 35565217, 2022). "This suggests that the extracellular release of HMGB1 is an important marker for the development of ICD response in tumor cells." (PMID 36466838, 2022). "It is shown that the silencing of HMGB1 can inhibit the growth of transplanted tumor, and it does play a radio-sensitization effect in vivo, and its mechanism is related to the PI3K/AKT/ATM signaling pathway." (PMID 36260180, 2022). "We provide a relatively comprehensive introduction of HMGB1 as a hub gene and a potential therapeutic biological marker for cancer progression from the perspective of clinical tumor samples." (PMID 36230798, 2022). "After ICD development in tumor cells, HMGB1 acts on TLR4 on DC and promotes optimal processing of tumor antigen toward crossover triggering T cells." (PMID 36212143, 2022). "Although extracellular HMGB1 is essential for the development of ICD-mediated immunogenicity, it is also associated with tumor progression." (PMID 36012593, 2022).
tumor (continued). "Although cisplatin is not considered a classical agent of immunogenic cell death, it induces HMGB1 release of tumor cells inducing the upregulation of costimulatory molecules on APCs intratumorally 22,30." (PMID 34975315, 2022). "Tumor-derived HMGB1 has been previously reported to resuscitate macrophage function in patients with ESCC; we here aim to assess the clinical relevance of HMGB1 in B cells." (PMID 34617194, 2022). "Radiation induces HMGB1 release in tumor microenvironment, triggering NETosis through TLR4; NETs enhance resistance to radiotherapy by suppressing CD8+ T cell infiltration." (PMID 35574410, 2022). "In contrast, the infiltration of anti-tumor effector cells, such as cytotoxic T-lymphocytes (CTLs) and natural killer (NK) cells, into the tumor microenvironment was accelerated in the HMGB1-knockout tumors." (PMID 35150340, 2022). "In this study, we demonstrated, for the first time, that extracellular HMGB1 released through secretory autophagy acts as a regulator of the crosstalk between GB cells and immune microenvironment that play major roles in tumor sensitivity towards TMZ." (PMID 35193644, 2022). "Similar in vivo tumor growth inhibition was also observed in the HMGB1-kockout clones established from B16F10 cells using an adeno-associated virus vector and an S. aureus Cas9 system (AAVpro CRISPR/SaCas9; Takara) with different gRNA." (PMID 35150340, 2022). "Analyses of plasma HMGB1 concentrations and HMGB1 expression levels in tumor tissue were only performed in a retrospective cohort with a small number of samples." (PMID 35328684, 2022). "HMGB1 is a DNA‐binding protein released during radiotherapy, and it is related to tumor radioresistance based on its DNA damage repair and autophagy functions." (PMID 35812184, 2022). "HMGB1 acted as a key regulator in mediating the crosstalk between GB cells and tumor-suppressive M1-like TAMs in the TME with the presence of the chemotherapeutic agent TMZ." (PMID 35193644, 2022). "Prolonged BK channel activation can result in overexpression of heat shock proteins (Hsp) 60, 70, 90 and gp96, release of one of the key DAMPs (HMGB1), and enhancement of the tumor immunogenicity of rat glioma T9 cells." (PMID 35562364, 2022). "The upregulation of HMGB1 expression in tumor tissues was also observed in our ESCC cohort; however, our data showed that HMGB1 was not an independent prognostic factor for ESCC." (PMID 34617194, 2022). "During the ICD response in tumor cells, HMGB1 is released extracellularly to bind to pattern recognition receptors (PRRs), including Toll-like receptors and receptors of advanced glycation end products (RAGE)." (PMID 36466838, 2022). "A recent study showed that HMGB1 acted as a ligand for toll-like receptor 2 (TLR2) on bone marrow-derived GB-infiltrating dendritic cells to elicit tumor regression." (PMID 35193644, 2022). "Several angiogenic factors were induced when B cells were co-cultured with tumor cells, and their levels were further upregulated in co-culture with HMGB1-overexpressing tumor cells." (PMID 34617194, 2022). "According to the experiment, compared with the control lentivirus group, the tumour weight and volume in the miR-495-3p lentivirus group were significantly decreased, and the tumour weight and volume in the HMGB1 lentivirus group were significantly increased." (PMID 35354479, 2022). "Paradoxically, the secretion of alarmin proteins (such as extracellular histones or HMGB1) by dying tumor cells has been previously shown to activate tumor antigen-specific T-cell immunity, via their action on TLR4 expressed by dendritic cells." (PMID 35562918, 2022). "And we found the application of HMGB1 silencing, especially combined with pathway inhibitor ly294002, slowed down the growth rate, the tumor volume and weight of xenografts, meanwhile, increased the apoptosis after radiation." (PMID 36260180, 2022).
tumor (continued). "High mobility group box 1 (HMGB1) and vascular endothelial growth factor D (VEGFD) are associated with lymphangiogenesis and tumor metastasis in GC." (PMID 36120367, 2022). "The baseline levels of HMGB1 showed a positive correlation with the initial tumor volume, and during follow-up, all HMGB1 levels were lower than the respective baseline values." (PMID 34671818, 2022). "Tumor growth in HMGB1-overexpressing cells was similar to the vector control group (labeled as EC18H in blue and EC18pc in green, respectively)." (PMID 34617194, 2022). "To understand how B cells are regulated within the HMGB1-enriched tumor nest, we initially investigated if HMGB1 binds to the surface of B cells." (PMID 34617194, 2022). "HMGB1 is released by UV-damaged epidermal keratinocytes to recruit neutrophils, which assist tumor cells in invading the blood vessels." (PMID 36060811, 2022). "We demonstrated that the extracellular release of HMGB1 increased after neutron beam irradiation, thereby highlighting its potential as an early biomarker for tumor response to BNCT." (PMID 35336794, 2022). "Released high mobility group box protein 1 (HMGB1) ligand binding to RAGE receptor in tumor cells promotes tumor progression." (PMID 35280439, 2022). "In the context of tumor, HMGB1 has a chemoattractant role for Treg, promotes their survival and enhances their immune inhibitory functions." (PMID 35053332, 2022). "HMGB1 has been investigated as a biomarker for tumor outcome and therapy response in tumor tissue as well as in blood plasma or serum samples." (PMID 34671818, 2022). "GC cell-derived exosomes induce neutrophil autophagy and tumor-promoting activation through the high mobility group box-1 (HMGB1)/TLR4/NF-κB signaling pathway, ultimately promoting the proliferation and migration of GC cells." (PMID 36341377, 2022). "HMGB1 in vivo significantly increased polarization of tumor-suppressive TAMs (M1-like) and inhibited intracranial GB growth." (PMID 35193644, 2022). "Cancer cells can produce DAMPs (e.g., HMGB1, ATP, and IL-1α) and tumor antigens (TAs) during necroptosis." (PMID 35399527, 2022). "The D1 domain of VCP and A box of HMGB1 were identified as the critical regions for their interaction, and D1 area was required for the tumor-promoting effects induced by VCP expression." (PMID 35562734, 2022). "Active secretion of HMGB1 occurs via immune cells, endothelial cells, platelets, neurons, astrocytes, and tumor cells during stress or secondary to other DAMP signals as reinforcement." (PMID 36012593, 2022). "On the one hand, CRT is an ‘eat me’ signal that triggers the phagocytosis of dying tumor cells by DCs, whereas HMGB1 binds to TLR4 and promotes DC maturation and tumor antigen presentation to CTLs." (PMID 35335881, 2022). "Similar to IL1β, HMGB1 is also involved in dendritic cell (DC) maturation, tumor antigen presentation, neutrophil polarization, and cytokine release in TME." (PMID 35432318, 2022). "The presence of docetaxel induces a higher expression profile of high mobility group box 1 (HMGB1) from tumor cells which in turn induces the expression of CXCL11 through NF-κB activation." (PMID 35634281, 2022). "Next, based on the GEPIA2 tool, the top 100 genes related to HMGB1 expression were obtained by combining all tumour expression data of TCGA." (PMID 35765707, 2022). "In the present study, elevated concentrations of extracellular HMGB1 affected local tumor growth and distant metastasis to the liver." (PMID 35328684, 2022). "HMGB1 acts as a tumour promoter in most of the tumours studied and has the potential to be used as a potential marker for prognosis." (PMID 35765707, 2022). "In vivo, xenograft tumor model was established in nude mice to study the effect of HMGB1 on radioresistance via PI3K/AKT/ATM Signaling Pathway." (PMID 36260180, 2022).
tumor (continued). "Under 808 nm laser irradiation, the temperature rose from 36.2 to 49.2 °C in the HepG2 bearing‐tumor tissue to induce ICD, resulting in releasing tumor associated antigens, CRT, ATP, and HMGB1." (PMID 35652198, 2022). "In the current study, levels of HMGB1 in the blood were significantly elevated when TTFields were applied, suggesting the release of HMGB1 by dying tumor cells." (PMID 36430552, 2022). "These levels were stably detected even when the size of the tumor decreased, suggesting that HMGB1 is a potential biomarker for the therapeutic efficacy of BNCT." (PMID 35336794, 2022). "Mouse neutrophil-derived NETs have been proven to trigger the release of HMGB1, and to promote the adhesion, proliferation, migration and invasion of tumor cells." (PMID 36230676, 2022). "This study analysed the genetic alteration, RNA expression profiling and DNA methylation of HMGB1 in more than 30 types of tumours." (PMID 35765707, 2022). "After exclusion of the patient with the largest tumor volume, HMGB1 at baseline was moderately correlated with the GTV (r = 0.48)." (PMID 34671818, 2022). "The interaction between mtDNA and HMGB1 also reportedly plays an important role in tumor growth via TLR9 signaling." (PMID 35801206, 2022). "Recent studies show that local RT creates an inflammatory microenvironment which is characterized by release of tumor antigens and DAMPs, which include high-mobility group protein B1 (HMGB1), adenosine triphosphate (ATP), and calreticulin." (PMID 36139006, 2022). "Collectively, this study provides an extensive analysis of B cells in the TME of ESCC, highlighting the prognostic significance of the pre-existing profile of HMGB1 and B-cell distribution inside and outside the tumor nest." (PMID 34617194, 2022). "Tumor-cell-derived exosomes transport high-mobility group box-1 (HMGB1) to interact with Toll-like receptor 4 (TLR4) and activate the neutrophil nuclear factor kappa-B (NF-κB) pathway." (PMID 36230676, 2022). "In summary, the pan‐cancer analysis of HMGB1 showed that the expression of HMGB1 was significantly related to the prognosis, genetic changes, immune cell infiltration and drug sensitivity of different tumours in cancer patients." (PMID 35765707, 2022). "This hypoxic environment results in focal areas of tumor cell necrosis with consequent release of DAMPs and alarmins, including HMGB1." (PMID 36012593, 2022). "Overexpression of HMGB1 in tumor tissue or elevation of HMGB1 levels in the serum of cancer patients is associated with poor prognosis in various malignancies." (PMID 34617194, 2022). "ICD stimulates antitumor immunity by different effects on cancer cells, including the promotion of surface expression of calreticulin (CRT) and high-mobility group box 1 (HMGB1) in tumor cells and the increasing of adenosine triphosphate (ATP) secretion." (PMID 35335881, 2022). "This suggests that HMGB1-RB interaction is essential for HMGB1-mediated transcriptional repression, cell growth inhibition, G1 cell cycle arrest, apoptosis induction and tumor growth inhibition." (PMID 35637945, 2022). "The half-life of HMGB1 is significantly affected by the extracellular environment such as hypoxic environment and high tumor cell densities." (PMID 35336794, 2022). "We consistently observed increased levels of angiogenesis-related cytokines in the CM of these co-cultures, in particular upon co-culture with HMGB1-expressing tumor cells." (PMID 34617194, 2022). "Although RAGE protein as a tumor cell receptor has been investigated, the contribution of HMGB1/RAGE signaling to tumor lymphangiogenesis on M2 macrophages has not yet been investigated, at least to the best of our knowledge." (PMID 35280439, 2022). "We performed quantitative scoring based on HMGB1 staining intensity by Fuji software and found that HMGB1 expression was significantly higher (p < 0.001) in tumor relative to normal tissues, representing about 86% (102/118) of all ESCC-paired cases." (PMID 34617194, 2022).
tumor (continued). "The tumor temperature was raised to 52.1 °C after laser irradiation, which induced a high level of expression of HMGB1 to ablate primary and distant tumors in an ICD model." (PMID 35652198, 2022). "HMGB1 regulates tumor cell growth, migration, and proliferation and plays a role in different intracellular biological processes through various species, including spliceosomes and the cell cycle." (PMID 36230798, 2022). "HMGB1 expression increases in many types of cancer, correlates with tumour invasion and metastasis, and relates to worse prognosis." (PMID 35344301, 2022). "A reduction in tumor-infiltrating macrophages and a protective effect against pancreatic cancer were observed in mice treated with deferiprone, vitamin E, and anti-HMGB1 antibodies." (PMID 35372083, 2022). "In GB7225 specimen with high level of autophagy (higher expression of LC3B, STX17 and lower expression of SQSTM1), HMGB1 in the nuclei and cytoplasm of tumor cells was significantly diminished." (PMID 35193644, 2022). "HMGB1 is a conical danger signal released from stressed or damaged cells, and its relevance to tumor progression has been documented." (PMID 36542153, 2022). "In conclusion, we demonstrated that knockout of HMGB1 in tumor cells converted cold tumors to hot tumors and suppressed in vivo tumor growth mediated by CTLs." (PMID 35150340, 2022). "The contribution of host immunity to the discrepancy between the in vitro and in vivo tumor growth of HMGB1-knockout clones was further analyzed using athymic nu/nu mice." (PMID 35150340, 2022). "As studies have shown the redox state was critical for action of HMGB1 and the signaling pathway it induced, we therefore proceeded to determine its oxidize/redox form in tumor niches." (PMID 36542153, 2022). "In the meantime, HMGB1, as one indicator of immunogenic cell death, was much higher in tumor samples collected from the Dinaciclib group." (PMID 35756622, 2022). "The binding of extracellular high mobility box 1 (HMGB-1) to toll-like receptor 4 (TLR4) convert the immature dendritic cells, D0, into the activated tumor-associated dendritic cells at a rate proportional to HMGB-1/(H0+HMGB-1), where H0 is constant." (PMID 35015785, 2022). "HMGB1 is known as a nuclear weapon in the tumor microenvironment as it can do many things, such as induce inflammation, interact with dendritic cells to promote anti-tumor T-cells, and so on." (PMID 36294824, 2022). "Treatment with PARPi suppressed the PARP-1/HMGB1 pathway and re-sensitized tumour cells to TRAIL induced cell death suggesting PARPi can sensitize tumours to NK-cell mediated apoptosis." (PMID 36159999, 2022). "Cells undergoing ICD release and express damage-associated molecular patterns (DAMPs), e.g., calreticulin, heat-shock protein 70 and 90, ATP, and/or HMGB1, which attract antigen-presenting cells (APCs) to the tumor side." (PMID 35892641, 2022). "A similar study found that hypoxia or starvation exerts an immune evasion effect by upregulating HMGB1 on tumor cell-released autophagosomes." (PMID 36233088, 2022). "HMGB1 levels as well as routine laboratory values were measured and clinical information was collected including tumor volume, infections, toxicity, and follow-up data." (PMID 34671818, 2022). "Our results indicated that knockout of HMGB1 in tumor cells actually converted cold tumors to hot tumors." (PMID 35150340, 2022). "Of the markers of immunogenic cell death described in the Consensus guideline in 2015, only HMGB1 can be measured in blood serum and plasma, as adenosine triphosphate (ATP) acts in the tumor microenvironment and calreticulin is exposed on tumor cells." (PMID 34671818, 2022). "In different syngeneic mouse models with large tumors, TEVs equipped with HMGB1 augment DC immunogenicity and elicit long-lasting antitumor immunity and tumor suppression." (PMID 36612080, 2022).